ATR (ATR checkpoint kinase)
Diseases named in the same sentence as ATR in open-access papers (continued):
Sharing a sentence is not in itself a finding about the gene and the disease.
Seckel syndrome (continued). "Mice with severe deficiency in ATR (a mouse model of Seckel syndrome) have small testes, and although infertile, successful in vitro fertilization could be achieved with ATRS/S sperm." (PMID 30566531, 2018). "Additional mutations in ATR were since linked to Seckel Syndrome." (PMID 30199583, 2018). "Seckel Syndrome is a rare genetic disease caused by mutations in several genes, including ATR." (PMID 30199583, 2018). "However Seckel syndrome, which is characterised as having low levels of ATR expression due to hypomorphic mutation of the ATR gene results in growth retardation and microcephaly." (PMID 28448462, 2017). "Only ATR had been identified as a causative gene for Seckel Syndrome by July 2009." (PMID 26919047, 2016). "However, Seckel syndrome individuals have a mutation in a splice site that results in the expression of just 10 % of the typical levels of ATR protein, which allows them to survive." (PMID 26438152, 2015). "However, recent data has shown that premature cellular senescence only occurs in a subset of PSs that includes WS, AT, HGPS, and ATR-SS (a version of Seckel Syndrome that has mutations in the AT and Rad3-related checkpoint kinase ATR)." (PMID 25214013, 2015). "As reference controls, two h-TERT immortalized skin fibroblast lines were included in the analysis: (i) 1BR, obtained from a normal ATR-proficient individual, and (ii) F02-98, derived from a patient afflicted with Seckel syndrome, characterized by hypomorphic ATR deficiency." (PMID 24416382, 2014). "For example, Seckel syndrome—a rare genetic disorder in which patients exhibit high levels of chromosomal instability and cancer—is caused by low expression of the DNA repair protein ATR, due to a hypomorphic mutation in the ATR gene." (PMID 22762011, 2012). "Interestingly, a mouse model carrying the ATR mutation (A2101G) associated with the Seckel syndrome in patients, recapitulated the symptoms of the human disease." (PMID 21054854, 2010). "Notably, a marked decrease in ATR levels (approximately 1/10th of normal levels) due to hypomorphic mutations in ATR mimicking Seckel syndrome induces a dramatic increase in DNA damage and suppresses tumor growth in cells experiencing suprathreshold RS induced by HRASG12V." (PMID 39456601, 2024). "It is unlikely transformed cells can survive without MRE11A, RAD50, ATRIP or PALB2 although significantly reduced levels may be tolerated, as evidenced by the ATR expression in Seckel syndrome and hypomorphic MRE11A and RAD50 mutations in ATLD and NBS-like disorder patients, respectively." (PMID 26438152, 2015). "ATR inactivation, e.g., in Seckel syndrome, results in not only microcephaly and ataxia but also behavioral changes in mice." (PMID 39951537, 2025). "Seckel syndrome patient cell lines show defects in phosphorylation of ATR substrates, instability of replication forks and disruption of activation of the cell cycle G2/M checkpoint." (PMID 36749285, 2023). "ATR levels were greatly decreased in human Seckel Syndrome, as well as in the mouse model of this syndrome by a homozygous mutation that creates mRNA splicing defects." (PMID 37511442, 2023). "All SLF2 and SMC5 mutant LCLs examined exhibited a significant increase in spontaneous replication fork stalling and fork asymmetry comparable to that observed in an LCL derived from an ATR-Seckel Syndrome patient." (PMID 36333305, 2022).
Seckel syndrome (continued). "Mutations in key mediators of the replication stress response, the mutually dependent partners ATR and ATRIP, are among the known causes of Seckel syndrome." (PMID 32994318, 2020). "Seckel syndrome is genetically heterogeneous, and mutations in DDR genes (ATRIP and ATR), DNA repair factors (NSMCE2, DNA2, TRAIP and CtIP) and components of the centrosome (NIN, CEP63, CEP152 and CENPJ) have been reported." (PMID 32994318, 2020). "ATM and ATR, whose loss of function leads to ataxia telangiectasia and Seckel syndrome, respectively, are the two master signaling kinases activated in response to DNA DSBs (ATM) or ssDNA stretches (ATR)." (PMID 32466131, 2020). "Mutations in ATR (ATM and rad3-related) and in ATRIP (ATR-interacting protein) are among the causes of Seckel syndrome." (PMID 32630049, 2020). "Other forms of Seckel syndrome are caused by mutations in genes associated with cell growth (TRAIP), genomic integrity and repair (ATR, NSMCE2, DNA2, and RBBP8), centrosome function (NIN, CEP63)." (PMID 29504900, 2018). "Western blot analysis of a fibroblast cell line derived from patient P1ATR confirmed a reduction in total ATR protein expression, as previously observed in cell lines derived from other Seckel Syndrome patients." (PMID 30199583, 2018). "Mutations in ATR (ataxia telangiectasia and RAD3-related) cause Seckel syndrome (ATR-SS), a microcephalic primordial dwarfism disorder." (PMID 26908596, 2016). "Hypomorphic mutations in ATR and ATM genes have been identified among patients carrying Seckel syndrome and ataxia-telangiectasia (A-T), respectively." (PMID 24500207, 2014). "While hypomorphic mutations in ATR and ATM genes have been identified among patients carrying Seckel syndrome and A-T, respectively, little was known about mutations in DNA-PKcs encoding RPKDC gene in human until recently." (PMID 24500207, 2014). "The generalized activation of apoptosis as a result of genomic instability in ATR-Seckel and Cenpjtm/tm mouse embryos provides one explanation for the proportionate dwarfism of Seckel syndrome patients." (PMID 23166506, 2012). "Here, we provide the first identification of a Seckel Syndrome patient with mutations in ATRIP, the gene encoding ATR–Interacting Protein (ATRIP), the partner protein of ATR required for ATR stability and recruitment to the site of DNA damage." (PMID 23144622, 2012). "Collectively, our analysis exposes an overlapping clinical manifestation between the disorders but allows an expanded spectrum of clinical features for ATR–ATRIP Seckel Syndrome to be defined." (PMID 23144622, 2012). "Microcephalic osteodysplastic primordial dwarfism type II protein PCNT and Seckel syndrome (also characterized by severe microcephaly) protein ATR are also centrosomal proteins." (PMID 21633703, 2011). "Mutations in pericentrin (PCNT2)/kendrin which encodes a structural centrosomal protein, were identified in several Seckel syndrome patients all of which exhibited defective ATR-pathway function." (PMID 19440510, 2008). "Haploinsufficiency of ATR, or some of its pathway components confers similar DDR defects to that of ATR-pathway defective Seckel syndrome cell lines." (PMID 19440510, 2008). "Likewise, radial/thumb anomalies observed in P2 are also reminiscent of Fanconi anaemia [MIM:PS227650] and ATR-related Seckel syndrome [MIM#210600], more rarely observed in LIG4-related MPD, Nijmegen and Bloom syndromes." (PMID 40114033, 2025). "Similarly, microcephaly also results from mutation in genes associated with S phase progression (ATR, ATRIP, CtIP—Seckel syndrome; DNA ligase IV—lig4 syndrome; XRCC4—microcephalic primordial dwarfism)." (PMID 34035299, 2021). "The ATR-Seckel syndrome is largely characterized by defects in the nervous system." (PMID 30486458, 2018).
Seckel syndrome (continued). "This is reflected by patients with the rare genetic disorder Seckel syndrome, to date originating from a small number of families carrying germline mutations in either ATR, or its interacting partner ATRIP, that result in reduced ATR protein levels." (PMID 24416382, 2014). "A previous report using an ATR hypomorphic Seckel syndrome cell line described an approximate two-fold increase of spontaneous micronuclei compared to wild-type and this difference was further augmented following treatment with the replication stress-inducing drug hydroxyurea." (PMID 24675793, 2014). "In contrast to cells from ATR-, CtIP-, CEP152- and PCNT-Seckel syndrome patients, we have shown that MEFs from Cenpj-deficient mice are not impaired in ATR-dependent DNA damage signaling but instead show an elevated frequency of extra centrioles, multipolar spindles, and near tetraploid karyotypes." (PMID 23166506, 2012). "The failure of ATR inhibitors in clinical trials, coupled with the still unknown links between the pathophysiology of ATR in patients with Seckel syndrome and other defects, has suggested that there are other incompletely understood roles of ATR that have been previously overlooked." (PMID 39456630, 2024). "However, the bi-allelic hypomorphic ATR splice site mutation 2101A→G, naturally found in Seckel syndrome patients, results in subtotal ATR protein depletion without significant effects on cancer cell growth or viability." (PMID 26755646, 2016). "In 2009, the OMIM database indicated the following loci for Seckel Syndrome: chromosomes 18p11-q11 (SCKL2, MIM:606744), 14q (SCKL3, MIM:608664) and 13q12 (SCKL4, MIM:613676), but causative mutations were only found in a single gene: ATR (ataxia-telangiectasia and RAD3-related protein, SCKL1)." (PMID 26919047, 2016). "Notably, however, genomic instability was not the result of defective ATR-dependent DNA damage signaling, as is the case for the majority of genes associated with Seckel syndrome." (PMID 23166506, 2012). "For instance, ATR-mediated phosphorylation of FANCD2 is essential for its monoubiquitination in response to DNA damage as shown by absence of FANCD2 monoubiquitination in ATR-deficient cells and cells from patients with Seckel syndrome, a disease resembling FA." (PMID 22737580, 2012). "They suggested that the haploinsufficiency of ATR may be responsible for the microcephaly and short stature observed in this patient based on the occurrence of these clinical features in ATR-defective Seckel syndrome." (PMID 19440510, 2008). "Compromised ATR-pathway function does not appear to be uniquely associated with Seckel syndrome." (PMID 19440510, 2008). "Hence, in agreement with the known genetic heterogeneity of this condition, whilst not all Seckel syndrome cases are caused by mutations in ATR itself, interestingly, all Seckel syndrome cell lines (ATR-S and non-ATR-S) exhibit compromised ATR-pathway function." (PMID 19440510, 2008). "Although ATR+/− mice have increased incidence of tumour formation, Seckel syndrome sufferers do not have an increased prevalence of cancer." (PMID 28448462, 2017). "But, NBS1 is also an ATR substrate and NBS patients exhibit microcephaly and growth retardation, clinical features associated with Seckel syndrome and not A-T." (PMID 19440510, 2008). "Notably, this phenotype was not significantly exacerbated by exposure to either APH or MMC, unlike LCLs from an ATR-Seckel Syndrome patient." (PMID 36333305, 2022).
lung carcinoma (56 papers, 2011 to 2025). "We showed that a GSK3β inhibitor selectively inhibited FHIT-deficient lung cancer by inhibiting the ATR/BRCA1/RAD51 signaling axis and BRCA1/RAD51 transcription, leading to the inhibition of HRR and genotoxic cell death." (PMID 39762409, 2025). "Ataxia Telangiectasia and Rad3-Related Protein (ATR) gene C.7667C >G (p.T2556S) mutation were found in 3 patients with familial lung cancer." (PMID 35712480, 2022). "In this study, we identified an interesting ATR mutation by whole-exome sequencing in three sisters of this family with lung cancers." (PMID 35712480, 2022). "We identified alterations associated with HRD, including mutations in ATM and ATR genes; specific deletions in stomach, bladder, and lung cancer; and BRCA-wild type breast, ovarian, and pancreatic cancers." (PMID 34572800, 2021). "Our study sheds light on the mechanism of action of PARP inhibitors in ATM-deficient cells and reveals that the addition of an ATR inhibitor is required to induce cell death in olaparib-treated ATM-deficient lung cancer cells." (PMID 31481733, 2019). "ATR encoded protein kinase is a master regulator of the DNA-damage response and its genetic alteration was associated with lung cancer risk." (PMID 29484121, 2018). "The striking conclusion from these analyses is that while ATM is mutated in a subset of lung cancers, ATR is amplified in subset of lung cancers." (PMID 26438152, 2015). "Next, we tested whether ATR-PrimPol-mediated RST is maintained in lung cancer cells with oncogenic KRAS mutation." (PMID 37591859, 2023). "We found a germline mutation in the ATR gene in three sisters of a Chinese family affected by familial lung cancer, which may be a genetic factor for lung cancer susceptibility." (PMID 35712480, 2022). "To investigate whether the reduction in cell viability in lung cancer cells after the combined WEE1/ATR inhibitor treatment was associated with increased S-phase DNA damage, we performed flow cytometry analysis of γH2AX induction." (PMID 34359691, 2021). "The mechanism through which inhibiting the ATR activity causes an increase of cisplatin-induced apoptosis in these lung cancer cells is unknown." (PMID 25937999, 2015). "The lncRNA ANRIL has been shown to promote HR-mediated DNA repair by maintaining ATR protein stability in lung cancer models." (PMID 41034557, 2025). "The Ataxia telangiectasia and Rad3-related (ATR) inhibitor ceralasertib in combination with the PD-L1 antibody durvalumab demonstrated encouraging clinical benefit in melanoma and lung cancer patients who progressed on immunotherapy." (PMID 38402224, 2024). "Based on the experimental results presented above, we posit that MSI2 enhances DNA damage repair through interactions with RBM17 and ATR, thereby increasing the radiation resistance of lung cancer cells." (PMID 38645664, 2024). "We found that knockdown of RBM17 disrupted the interaction between MSI2 and ATR post‐irradiation and increased the radiosensitivity of lung cancer cells." (PMID 38645664, 2024). "In a recent investigation by Rødland and colleagues, administration of a Wee1 inhibitor led to augmented phosphorylation of Chk1 S317 and ATR expression in all lung cancer cells." (PMID 37296592, 2023). "Herein, we investigated the association of potentially functional SNPs in ATM, ATR and CAT with platinum-based chemotherapy outcome of lung cancer patients." (PMID 36969849, 2023). "PURPOSE: To explore the relationship between ATM, ATR and CAT polymorphisms and prognosis of lung cancer patients received platinum-based chemotherapy." (PMID 36969849, 2023).
lung carcinoma (continued). "In this study, we continue to focus on the germline mutation of genes in lung adenocarcinoma and we have identified seven different variants (SMG5, RAB3GAF2, EI24, XDH, PTPRA, ATR, GSTZ1) in three sibling patients suffering from lung cancer." (PMID 35712480, 2022). "We identified several germline and somatic mutations (e.g., BRCA1/2, PALB2, ATM, and ATR mutations) associated with HRD phenotype in ovarian, breast, pancreatic, stomach, bladder, and lung cancer." (PMID 34572800, 2021). "Regardless, our results further extend the robustness of previous observations to additional lung cancer cell lines, as we observed that A3A expression provoked particularly strong sensitivity to ATR inhibitors, among the interventions tested." (PMID 33788831, 2021). "The ATR kinase encoded by ATR is implicated in the DNA damage response (DDR), and is involved in lung cancer development." (PMID 34195081, 2021). "Together, these results suggest that despite elevated replication initiation, the reduction in viability upon combined treatment with WEE1 and ATR inhibitors cannot simply be explained by an increased induction of S-phase DNA damage in the lung cancer cells." (PMID 34359691, 2021). "After multiple-testing correction, 112 SNPs in eight genes (ATR, EGFR, MET, PIK3R1, PIK3R3, PTPN2, STAT3, and STAT5A) remained significantly associated with lung cancer risk with FDR <0.20." (PMID 28400551, 2017). "Our CHK1 phosphorylation studies revealed that the presence of caffeine caused a decrease of cisplatin-induced CHK1 phosphorylation at Ser317/Ser345 in both HTB182 and CRL5985 lung cancer cells, suggesting an inhibited ATR activity in these cells." (PMID 25937999, 2015). "Our results suggest that the presence of caffeine increases the cisplatin-induced lung cancer cell killings by inhibiting ATR but inducing ATM activation, resulting in an increase in expression of PUMA protein and an increase in apoptosis." (PMID 25937999, 2015). "All of these results suggest that the presence of caffeine increases the cisplatin-induced cell killing in both CRL5985 and HTB182 lung cancer cells by inhibiting ATR activity, resulting in an increase in apoptosis." (PMID 25937999, 2015). "Altogether, inhibitors of ATR, Chk1, and Wee1 are emerging as new cancer treatment agents, likely to be useful in lung cancer treatment." (PMID 25774168, 2015). "Synergistic effects have also been reported between inhibitors of ATR/Chk1/Wee1 and conventional lung cancer treatments, such as gemcitabine, cisplatin, or radiation." (PMID 25774168, 2015). "Analyses of ATM serine 1981 and Chk1 serine 345 phosphorylation, and FANCD2 monoubiquitination revealed that ATM and ATR kinase activation and FA pathway signaling are intact in the lung cancer cell lines examined." (PMID 26438152, 2015). "Since the Ser317/Ser345 of CHK1 protein are phosphorylated primarily by ATR kinase, these results suggest that the ATR activity was inhibited in these lung cancer cells." (PMID 25937999, 2015). "To address this we profiled VX-970, the first clinical ATR inhibitor, in a series of in vitro and in vivo lung cancer models and compared it with an inhibitor of the downstream kinase Chk1." (PMID 25010037, 2014). "We used the ATR inhibitor VE-821 and the DNA-PK inhibitor NU-7441 as inhibitors of HRR and NHEJ, respectively, and analyzed their synthetic lethal effects on FHIT-deficient lung cancer cells." (PMID 39762409, 2025). "In summary, we suggested that MSI2 may impact the radiation‐induced DNA damage response and, consequently, the radiation sensitivity of lung cancer cells through its interaction with ATR." (PMID 38645664, 2024). "In addition to CHO cells, we investigated the impact of ATM and ATR on the intra- S-phase checkpoint in the human lung carcinoma cell line, A549." (PMID 35886852, 2022). "However, all four lung cancer cell lines showed a clear G2 arrest at 17 hours after irradiation, which was abrogated upon ATR inhibition." (PMID 36387237, 2022).